SPATA2L (spermatogenesis associated 2 like)
Synonyms: C16orf76; MGC26885; tamo
Tractability: PROTAC: ubiquitination databases record sites on it; its protein half-life has been measured.
Gene: Protein-coding gene on chromosome 16 (89,696,357 to 89,701,705, reverse strand). Ensembl gene ENSG00000158792.
Subcellular location (Human Protein Atlas): Mitochondria; Nucleoplasm; Cytosol
Gene Ontology:
Molecular function: protein binding
Cellular component: cytoplasm
Genetic constraint (gnomAD): Loss-of-function variants: 8 observed, 6.44 expected, observed/expected ratio (o/e) 1.24, 90% interval 0.71 to 1.88. That is too few expected variants to judge how well the gene tolerates losing a copy. Missense variants: 671 observed, 509.82 expected, observed/expected ratio (o/e) 1.32, 90% interval 1.24 to 1.4. Synonymous variants: 358 observed, 243.68 expected, observed/expected ratio (o/e) 1.47, 90% interval 1.35 to 1.6.
Homologues: Orthologues: chimpanzee SPATA2L (99% identical), macaque SPATA2L (99% identical), guinea pig SPATA2L (88% identical), mouse Spata2l (86% identical), rat Spata2L (85% identical), dog SPATA2L (82% identical), pig SPATA2L (82% identical), tropical clawed frog spata2l (30% identical), zebrafish spata2l (20% identical), Drosophila melanogaster tamo (18% identical). Paralogues in human: SPATA2 (18% identical).
Diseases named in the same sentence as SPATA2L in open-access papers:
SPATA2L is named in the same sentence as 5 diseases in open-access papers, as found by Europe PMC text mining. Sharing a sentence is not in itself a finding about the gene and the disease. The quoted sentences say what the papers report.
vitiligo (3 papers, 2021 to 2024). Generalized well circumscribed patches of leukoderma that are generally distributed over symmetric body locations and is due to autoimmune destruction of melanocytes. "In addition, gene SPATA2L have been identified to be associated with vitiligo in a recent study, and the inverse relationship between vitiligo and NMSC was suggested in many research." (PMID 34040636, 2021). "By integrating omics data, we identified two newly putative functional genes (SPATA2L and CDK10) associated with vitiligo and further validated CDK10 by qRT-PCR in independent samples." (PMID 33679896, 2021).
melanoma (1 paper, 2024). A malignant, usually aggressive tumor composed of atypical, neoplastic melanocytes. "For example, genes in cluster 2 (SPIRE2, SPATA2L), 3 (OCA2, DBNDD1, FANCA, GAS8) and 4 (URAHP, DEF8, CPNE7, MC1R) underlie the associations between melanoma and pigmentation traits." (PMID 38308491, 2024).
tuberculosis (1 paper, 2022). A chronic, recurrent infection caused by the bacterium Mycobacterium tuberculosis. "Lastly, the region on BTA 18 was reported as a candidate region for tuberculosis resistance, milk, and fertility traits including spermatogenesis-associated proteins 33 and 2L (SPATA33 and SPATA2L) in the extended regions of 250 kb." (PMID 36712857, 2022).
SPATA2L also shares sentences with these, for which no sentence is quoted: pancreatic cancer (1 paper); skin cancer (1).